ARL13B (ARF like GTPase 13B)
Description:
Cilium-specific protein required to control the microtubule-based, ciliary axoneme structure. May act by maintaining the association between IFT subcomplexes A and B. Binds GTP but is not able to hydrolyze fit; the GTPase activity remains unclear. Required to pattern the neural tube. Involved in cerebral cortex development: required for the initial formation of a polarized radial glial scaffold, the first step in the construction of the cerebral cortex, by regulating ciliary signaling. Regulates the migration and placement of postmitotic interneurons in the developing cerebral cortex. Plays a role in ciliar trafficking of phosphatidylinositol phosphatase INPP5E in ciliogenesis. May regulate ARF6- and RAB22A-dependent endocytic recycling traffic.
Synonyms: ARL2L1; DKFZp761H079; JBTS8
Tractability: Antibody: UniProt places it where antibodies can reach, with high confidence; its Gene Ontology location is reachable by antibodies, with medium confidence. PROTAC: UniProt records ubiquitination sites on it; ubiquitination databases record sites on it.
Gene: Protein-coding gene on chromosome 3 (93,980,139 to 94,055,678, forward strand). Ensembl gene ENSG00000169379.
Subcellular location: Cell projection, cilium membrane; Cell projection, cilium; Cell membrane; Cytoplasm, cytoskeleton
Subcellular location (Human Protein Atlas): Microtubules; Primary cilium; Primary cilium transition zone; Acrosome; Basal body; Cytokinetic bridge; End piece; Equatorial segment; Mid piece; Principal piece
Pathways (Reactome):
Autophagy: Aggrephagy; Chaperone Mediated Autophagy; Late endosomal microautophagy
Signal Transduction: RHOJ GTPase cycle; RHOQ GTPase cycle
Organelle biogenesis and maintenance: ARL13B-mediated ciliary trafficking of INPP5E
Gene Ontology:
Molecular function: protein binding; GTP binding; GTP-dependent protein binding; GTPase activity
Biological process: cilium assembly; formation of radial glial scaffolds; interneuron migration from the subpallium to the cortex; neural tube patterning; non-motile cilium assembly; receptor localization to non-motile cilium; smoothened signaling pathway; kidney development
Cellular component: 9+0 non-motile cilium; ciliary transition zone; cilium; intercellular bridge; microtubule cytoskeleton; ciliary membrane; cytosol; motile cilium; non-motile cilium; axoneme; cytoskeleton; plasma membrane
Genetic constraint (gnomAD): Loss-of-function variants: 35 observed, 51.92 expected, observed/expected ratio (o/e) 0.67, 90% interval 0.51 to 0.89. The upper end of that interval is the gene's LOEUF score, 0.89, which puts it in group 3 of 6, group 1 being the genes least tolerant of losing a copy. Missense variants: 502 observed, 510.62 expected, observed/expected ratio (o/e) 0.98, 90% interval 0.91 to 1.06. Synonymous variants: 171 observed, 172.01 expected, observed/expected ratio (o/e) 0.99, 90% interval 0.88 to 1.13.
Gene-disease validity (ClinGen):
ClinGen rates the evidence that ARL13B causes each of these diseases.
Joubert syndrome (autosomal recessive): Definitive. Joubert syndrome (JS) is characterized by congenital malformation of the brainstem and agenesis or hypoplasia of the cerebellar vermis leading to an abnormal respiratory pattern, nystagmus, hypotonia, ataxia, and delay in achieving motor milestones.
Homologues: Orthologues: chimpanzee ARL13B (99% identical), macaque ARL13B (96% identical), dog ARL13B (86% identical), pig ARL13B (84% identical), rabbit ARL13B (84% identical), rat Arl13b (81% identical), mouse Arl13b (80% identical), guinea pig ARL13B (74% identical), tropical clawed frog arl13b (65% identical), zebrafish arl13b (60% identical). Paralogues in human: ARL13A (21% identical), ARF1 (17% identical), ARF3 (17% identical), ARF4 (16% identical), ARL2 (16% identical), ARL4A (16% identical), ARF5 (15% identical), ARL3 (15% identical), TRIM23 (15% identical), ARL1 (15% identical), ARL6 (15% identical), ARL4C (15% identical), and 18 more.
Diseases named in the same sentence as ARL13B in open-access papers:
ARL13B is named in the same sentence as 55 diseases in open-access papers, as found by Europe PMC text mining. Sharing a sentence is not in itself a finding about the gene and the disease. The quoted sentences say what the papers report.
Joubert syndrome (32 papers, 2013 to 2025). "Biallelic pathogenic variants in ARL13B are a known cause of Joubert Syndrome 8 (OMIM# 612291), which has a phenotype that overlaps with the affected individuals in this family." (PMID 40730687, 2025). "Since mutations in ARL13B gene have been associated with Joubert syndrome, a systemic ciliopathy accompanied by retinal dystrophy, the localization of ARL13B in photoreceptors has been discussed in various studies, with variable conclusions." (PMID 38979372, 2024). "These proteins include Arl13b, a Joubert syndrome associated protein which causes cystic renal disease when conditionally deleted in renal epithelial cells in the mouse." (PMID 36276950, 2022). "We first tested the ability of R382W TULP3 to facilitate the ciliary transport of Arl13b, a small G-protein associated with Joubert’s Syndrome that requires Tulp3 for transport into the cilium in kidney cells." (PMID 36276950, 2022). "A similar approach, using the valuable HDBR tissue bank has been performed, using in situ hybridisation for studying the expression of ARL13B, another cause of Joubert syndrome." (PMID 33297941, 2020). "Mutations in Arl13b are known to result in defective cilia formation leading to Joubert syndrome, a ciliopathy characterized by neurological abnormalities and cognitive delay." (PMID 32122360, 2020). "Given that the functional interactors of ERICH3 are all associated with ciliary diseases such as Joubert syndrome (ARL13B, INPP5E) and Bardet Biedl syndrome, ERICH3 represents an attractive candidate for mutations in unresolved ciliopathies." (PMID 31712586, 2019). "Mutations in Arl13b are associated with Joubert syndrome (a ciliopathy), and Arl13b-null animals display a wide range of ciliary defects that compromise ciliogenesis, cilia length extension, ciliary motility and sonic hedgehog signaling." (PMID 30097558, 2018). "Failure to activate Arl3 function through loss of the Arl3 GEF Arl13b causes Joubert syndrome, usually with multiple organ involvement." (PMID 28444310, 2017). "Here we show that the ciliary G-protein Arl13B mutated in Joubert syndrome is the GEF for Arl3, and its function is conserved in evolution." (PMID 26551564, 2015). "Previous studies have shown that mutations in the gene that encodes Arl13B can cause Joubert syndrome in humans." (PMID 26551564, 2015). "Overexpression of Arl13B in mammalian cell lines leads to an increased Arl3·GTP level, whereas Arl13B Joubert-Syndrome patient mutations impair GEF activity and thus Arl3 activation." (PMID 26551564, 2015). "Amongst the possible regulators, several small GTPases have been associated with the flagellum: ARL-13b is involved in the stabilization of ciliary assembly in C. elegans and its mutations are associated with a ciliopathy named Joubert syndrome." (PMID 24843028, 2014). "Recent work has shown that SUMOylation of the small GTPase ARL-13, the worm ortholog of Arl13B that is mutated in the ciliopathy Joubert syndrome, regulates the proper ciliary targeting of various sensory receptors and the corresponding sensory functions." (PMID 23985042, 2013). "To investigate mechanisms underpinning protein sequestration to ciliary membranes, we assessed how Joubert syndrome-associated ARL13B/ARL-13 is targeted to and restricted at ciliary membranes." (PMID 24339792, 2013). "Here, we investigated how Joubert syndrome-associated ARL13B/ARL-13 is compartmentalized at subciliary membranes." (PMID 24339792, 2013). "Additionally, the expression of ARL13B variants underlies the neurological defects in Joubert syndrome patients." (PMID 39905509, 2025). "Dysregulation of ARL13B has been linked to ciliopathies such as Joubert syndrome." (PMID 41425088, 2025). "Interestingly, some Arl13b mutations identified in individuals with Joubert syndrome have been shown to hinder Arl13b localization to the primary cilium." (PMID 39157903, 2024). "The arl13b-deficient zebrafish can serve as a model organism for studying Joubert syndrome." (PMID 32812127, 2020).
Joubert syndrome (continued). "In humans, mutations in ARL13b cause Joubert Syndrome, whereas mutations in RP2 cause X-linked RP." (PMID 28444310, 2017). "Furthermore INPP5E localization studies for Arl13B patient mutations associated with Joubert syndrome will deepen our understanding of the molecular basis of ciliopathies." (PMID 27063844, 2016). "Mutations in ciliary proteins such as CEP290, ARL13B or INPP5E in Joubert syndrome may lead to important neurological disturbances in cerebellar development and defective formation of adult neuronal stem cells regions." (PMID 23205631, 2013). "Arl13b plays an evolutionarily conserved role in ciliary movements and transport in ascidians, and participates in Sonic hedgehog signaling in other systems; mutations in this gene lead to Joubert syndrome in humans, and to a related mutant phenotype in zebrafish." (PMID 39769393, 2024). "In fact, mutations in Arl13B, the Arl3 GEF, cause the syndromic ciliopathy Joubert syndrome and can cause a reduction of Arl3 activation." (PMID 36598133, 2023). "Furthermore, we reveal that some Joubert syndrome mutations perturb INPP5E ciliary targeting, and clarify how each CLS works: (i) CLS4 recruits PDE6D, RPGR and ARL13B, (ii) CLS2-CLS3 regulate association to TULP3, ARL13B, and CEP164, and (iii) CLS1 and CLS4 cooperate in ATG16L1 binding." (PMID 36063381, 2022). "Furthermore, genetic mutations in Arl13b and INPP5E are linked to the ciliopathy Joubert syndrome." (PMID 29244804, 2017). "However, as defective axoneme acetylation is not observed in CEP41- or ARL13B-deficient cells, we reason that defective axoneme glutamylation is probably the major driver for the development of ciliopathy phenotypes observed in Joubert syndrome patients." (PMID 33748109, 2021). "Besides ARL13B and ARL3 that are involved in human Joubert syndrome, the IFT complex, HYDIN, and the ODA complex are all confirmed human ciliopathy genes." (PMID 39231220, 2024).
ciliopathy (19 papers, 2013 to 2025). A genetic disorder of the cellular cilia or the cilia anchoring structures, the basal bodies, or of ciliary function. "Mutations in some members of the ARL subfamily (e.g. ARL3, ARL6, ARL13B) are associated with ciliopathy diseases, emphasising that there is still a wealth of clinically relevant cellular mechanisms to undercover in the ARF family." (PMID 37622523, 2023). "In humans, mutations of ARL13B cause Joubert syndrome, a ciliopathy characterized by brain malformations, combined with polydactyly and renal cyst formation." (PMID 34209603, 2021). "Further experiments inducing full loss of arl13b or unc119b function in a cep290-deficient larvae may show more severe ciliopathy phenotypes." (PMID 34155518, 2021). "Normally, the gene ARL13B has been associated with JBTS and the ciliopathy spectrum; in this case, RP-2310 had rod-cone dystrophy and Asperger syndrome, which is part of the autism spectrum disorders (ASD)." (PMID 34448047, 2021). "Mutations in Arl6 –the first member of the Arl family found mutated in a human ciliopathy – cause BBS, whereas mutations in Arl13B lead to JS." (PMID 26551564, 2015). "Further study is needed to determine whether the serum levels of cilium-related proteins, such as ARL13B, could be detected to diagnose ciliopathy in the future." (PMID 34209603, 2021). "The primary cilium is a structure important for both mechano-transduction and signaling, and perturbations of this organelle lead to a special category of diseases called ciliopathies, which can include severe cortical disorganization, as mentioned in the case of Arl13b." (PMID 25729350, 2015). "We identified 10 genes (STK38L, TUBB2A/B, CCNO, ARL13B, RFX2, RAB23, TUBA1C, CEP170B, and SPATA7) that are established or candidate ciliopathy genes." (PMID 34485842, 2021).
medulloblastoma (7 papers, 2018 to 2024). A malignant, invasive embryonal neoplasm arising from the cerebellum. "Arl13b has been recently implicated in promoting both gastric tumor growth and medulloblastoma." (PMID 30410731, 2018). "And ARL13B disruption in PC can lead to decreased Shh signaling in mouse medulloblastoma cell cultures." (PMID 39364348, 2024). "IFT88 is an intraflagellar transport protein and ARL13B is a regulatory GTPase; both are required for ciliogenesis and activation of canonical hedgehog signaling pathway in basal cell carcinoma and medulloblastoma." (PMID 36394953, 2023). "In medulloblastoma, ARL13B depletion was reported to lead to a decrease in cilia-dependent oncogenic Hh signaling." (PMID 32426352, 2020). "The role of ARL13B in medulloblastoma and gastric cancer progression, dependent on cilia and Hh signaling was described recently." (PMID 32426352, 2020). "Relevantly, disruption of Arl13b inhibits Shh signaling over-activation and suppresses medulloblastoma formation." (PMID 32122360, 2020). "This extends recent reports demonstrating a role for Arl13b in gastric tumorigenesis and medulloblastoma formation." (PMID 31569511, 2019). "A recent study has shown that the disruption of Arl13b inhibits cilia-dependent oncogenic Shh overactivation in medulloblastoma." (PMID 30410731, 2018). "We stained a small panel of SHH medulloblastoma samples derived from young patients for ARL13B, a marker for primary cilia, and confirmed that there is large variation in the number of ciliated cells between different patients, with some tumors hardly expressing any primary cilia." (PMID 35535520, 2022). "Moreover, recent studies showed that Arl13b promotes gastric carcinogenesis, cell migration and invasion, as well as medulloblastoma formation." (PMID 31569511, 2019).
glioblastoma (6 papers, 2018 to 2024). The most malignant astrocytic tumor (WHO grade IV). "This is of potential significance because ARL13B-mediated signaling associated with glioblastoma cilia is linked to both tumor growth and TMZ resistance in vivo." (PMID 35359402, 2022). "By increasing the activity of the VEGFA-VEGFR2 pathway, ARL13B stimulates angiogenesis and glioblastoma tumor growth." (PMID 38892305, 2024). "The presence of primary cilia in glioblastoma tissues was confirmed by staining for ARL13B and γ-tubulin in biopsy specimens from patients with glioblastoma, which is in line with other studies indicating that glioblastoma tumors contain ciliated cells." (PMID 36394953, 2023). "TMZ has recently been reported to increase the frequency and length of ARL13B+ cilia patient-derived glioblastoma cells." (PMID 35359402, 2022). "An increased EC expression of ARL13B has been correlated with a poor prognosis in glioblastomas." (PMID 38892305, 2024). "KLHDC8A mRNA expression correlated with the IFT88 and ARL13B expression in glioblastoma tissues." (PMID 36394953, 2023). "ARL13B was upregulated in glioblastoma tissues compared with normal brain tissues." (PMID 36394953, 2023). "Here, we used piggyBac-mediated transgenesis to generate patient-derived glioblastoma (GBM) cell lines that stably express Arl13b:GFP in their cilia." (PMID 30410731, 2018). "TMZ can stimulate expression of ARL13B and an interaction between ARL13B and the purine biosynthesis pathway as a mechanism to drive TMZ chemoresistance in glioblastoma." (PMID 35359402, 2022). "Previous studies have showed that increasing ARL13B in glioblastoma cells promoted ciliary SMO accumulation, independent of exogenous SHH addition." (PMID 37830570, 2023). "We first examined the relationship of ARL13B expression and another key ciliogenesis gene, IFT88, with the expression of other SHH pathway genes (SMO, GLI2, and SHH) in low-grade glioma (LGG) and high-grade glioblastoma (GBM) using TCGA datasets." (PMID 37830570, 2023). "An in vitro study suggests that it may also play a role in glioblastoma angiogenesis, which is also true for the homeodomain transcription factor paired-related homeobox 1 (Prrx1) and for a GTPase named ADP-ribosylation factor-like protein 13B (ARL13B)." (PMID 37626776, 2023).